RNU6-559P (RNA, U6 small nuclear 559, pseudogene)
Gene: Small nuclear RNA gene on chromosome 9 (15,143,289 to 15,143,386, forward strand). Ensembl gene ENSG00000251960.
Homologues: Orthologues: chimpanzee U6 (97% identical), macaque U6 (88% identical). Paralogues in human: RNU6-1020P (88% identical), RNU6-1011P (87% identical), RNU6-1124P (86% identical), RNU6-12P (85% identical), RNU6-13P (85% identical), RNU6-24P (85% identical), RNU6-32P (85% identical), RNU6-33P (85% identical), RNU6-39P (85% identical), RNU6-1 (84% identical), RNU6-1060P (84% identical), RNU6-1117P (84% identical), and 1286 more.